AQP2 (aquaporin 2)
Diseases named in the same sentence as AQP2 in open-access papers (continued):
Sharing a sentence is not in itself a finding about the gene and the disease.
Polyuria (continued). "AVP-stimulated AQP2 expression depends on prorenin activation of PRR, conditional deletion of PRR in the CD, and the whole nephron causes a common polyuria phenotype with consistent inhibition of renal AQP2 and V2R expression and AVP sensitivity." (PMID 33868005, 2021). "Along with this decrease, we also detected a defect in the urinary concentration mechanism and polyuria, and a reduced level of renal AQP2 expression." (PMID 31185935, 2019). "In a previous study, reduced expression of water channels AQP2 was found to be correlated with cisplatin-induced polyuria and end-organ resistance in rats." (PMID 29472315, 2018). "Thus, we suggest that AQP-2 plays an important role in alleviating dehydration caused by poorly uncontrolled diabetes with polyuria and that DWI with ultra-high b-values may be valuable for noninvasive early detection and discriminative diagnosis of diabetic nephropathy." (PMID 29708187, 2017). "Our data show that ablation of PKCα preserves AQP2 and UT-A1 protein expression and localization in lithium-induced NDI, and prevents the development of the severe polyuria associated with lithium therapy." (PMID 25006961, 2014). "Recently, Fernandez-Llama showed that CD water channels, AQP2, 3, 4 as well as proximal tubule AQP1 expression levels were significantly decreased in association with polyuria in response to ischemia." (PMID 20142913, 2008). "The authors could show that chloroquine ameliorated LiCl-induced polyuria in mice and that it had a protective effect on the Aqp2 protein level in cortical collecting duct cell lines." (PMID 32340354, 2020). "In addition, secretin receptor knockout mice exhibit mild polyuria, polydipsia, and reduced renal expression of AQP2." (PMID 29478202, 2018). "The study suggests that up-regulated AQP5, perhaps by reducing AQP2 membrane localization, may contribute to polyuria." (PMID 27455244, 2016). "Importantly, these studies demonstrated long-term parallel reduction in AQP2 expression and development of polyuria, decreased urine osmolality, and increased free water clearance, indicating a functional association between AQP2 abundance and the capacity to excrete free water." (PMID 37440209, 2023). "Our findings demonstrate that UA reduces the expression of AQP2, AQP3 and AQP4 in an NFκB-dependent manner, which contributes to the polyuria phenotype in the subjects with HUA." (PMID 40271210, 2025). "Collectively, our findings demonstrate that UA reduces the expression of AQP2, AQP3 and AQP4 in an NFκB-dependent manner, which contributes to the polyuria phenotype in subjects with HUA." (PMID 40271210, 2025). "In the kidney, AQP5 acts as a negative regulator of aquaporin-2 (AQP2) trafficking, thereby impairing renal water reabsorption and inducing polyuria." (PMID 36768212, 2023). "The central role of specific AQP2 and AVPR2 in regulating water homeostasis will provide correlations in case of CKD with polyuria." (PMID 34903939, 2021). "On the other hand, renal unresponsiveness to vasopressin or defective AQP2 function in patients with congenital NDI impairs AQP2 activity and water reabsorption, resulting in polyuria." (PMID 29478202, 2018). "As AQP2 membrane localisation is essential for water reabsorption, it is reasonable to conclude that this AQP5 -related disruption of AQP2 membrane trafficking is responsible for the polyuria seen in patients with DN." (PMID 34843700, 2022). "Mice lacking AQP2 suffer severe polyuria, with average basal daily urine volumes approximately equivalent to body weight and are totally unable to concentrate urine." (PMID 30845906, 2019). "A mutation in or lack of genes, such as those for aquaporin 2 (AQP2), Barttin, sodium-potassium-chloride cotransporter 2 (NKCC2), or V2 vasopressin receptor, results in polyuria and hydronephrosis, and polyuria can overwhelm the urine excretion capacity to induce hydronephrosis." (PMID 30708991, 2019).
Polyuria (continued). "Interestingly, lithium treatment does not result in polyuria and AQP2 downregulation in mice lacking mPGES-1, suggesting mPGES-1-derived PGE2 is a critical player in the pathogenesis of NDI." (PMID 29186911, 2017). "In this report, we uncover a new mechanism by which Dot1l regulates water homeostasis, and identify Aqp5 as a potential novel target of Dot1a, a binding partner of Aqp2, a negative trafficking regulator of Aqp2, and thus the potential missing component linking disrupted Dot1l to polyuria." (PMID 23326416, 2013). "Thus, dysregulation of AQP2 due to the absence of vasopressin plays a major role in the development of polyuria." (PMID 20142913, 2008). "Thus, long-term administration of empagliflozin could disrupt water reabsorption via AQP2 and increase non-glycosuric free water diuresis, contributing partially to polyuria." (PMID 30941057, 2019). "This lack of water channels (AQP-2) and ADH would be responsible for the polyuria and urine concentration defect that occur in cisplatin-induced AKI42,43." (PMID 33247145, 2020).
diabetes insipidus (40 papers, 2008 to 2025). A disorder characterized by excretion of large amounts of urine, accompanied by excessive thirst. "Lithium ion is a known nephrotoxicant, whose mechanism of toxicity is related to the inhibition of AQP-2 transport to the cell membrane, thereby causing diabetes insipidus." (PMID 32635323, 2020). "PDE4 also inhibits AQP2 shuttling at the plasma membrane and its hyperactivity causes nephrogenic diabetes insipidus (NDI) in a mouse model, thus suggesting a crucial role of PDEs in the diuresis." (PMID 27213818, 2016). "The development of chronic ER stress causing medullary atrophy with inability to elevate Aqp2 protein levels represents a molecular basis for the nephrogenic diabetes insipidus." (PMID 26839400, 2016). "Expression of RIαB in the collecting duct cells of the kidney disrupts aquaporin-2 expression and function, causing diabetes insipidus (M. Gilbert, L. Yang, and G.S. McKnight, unpublished observations)." (PMID 21533282, 2011). "The novel AQP2 c.398T > A (p.Val133Glu) variant described herein was associated with early and severe clinical manifestations, underscoring the importance of genetic testing in atypical or treatment-refractory presentations of diabetes insipidus." (PMID 40806548, 2025). "Vasopressin receptor type 2 and AQP2 loss‐of‐function mutations: diabetes insipidus." (PMID 35909256, 2023). "The alteration in AQP2 (aquaporin-2) gene causes misfolding of AQP-2 protein that may lead to developing diabetes insipidus in mammals." (PMID 31941036, 2020). "For example, mutations in the V2R or the AQP2 gene cause diabetes insipidus, a disease characterized by an excessive excretion of hypotonic urine (up to 20 l/day); elevated levels of AVP can cause or are associated with e.g., hyponatremia, liver cirrhosis or heart failure." (PMID 32164329, 2020). "Acquired diabetes insipidus is seen in cases such as long term lithium therapy where AQP2 subcellular localization can become dysregulated resulting in reduced surface localization and therefore loss of AQP2 function." (PMID 30934923, 2019). "Defects preventing the insertion of AQP2 into the plasma membrane cause diabetes insipidus." (PMID 26903868, 2016). "Recently, using a targeted deletion strategy, we generated a PC‐specific Nfat5‐KO mouse model using an Aqp2‐driven Cre‐deleter (Aqp2Cre+/−Nfat5fl/fl) that results in a diabetes insipidus‐like phenotype." (PMID 39874047, 2025). "Concurrent CaSR activation in the distal convoluted tubules suppresses aquaporin-2 expression, inducing nephrogenic diabetes insipidus and further reducing water reabsorption." (PMID 41141160, 2025). "We have previously demonstrated that adenine causes nephrogenic diabetes insipidus with salt wasting, at least, by directly interfering with vasopressin V2 receptor signaling and subsequent downregulation of both NKCC2 and AQP2 in the kidney." (PMID 40794384, 2025). "For example, sampling of urine Aquaporin-2 (AQP-2), an integral water channel, has been previously utilized as a marker for water balance disorders, such as diabetes insipidus." (PMID 38398672, 2024). "Metformin increases urine osmolality in a rat model of congenital diabetes insipidus by stimulating urea transporter (UT-A1), aquaporin 2 (AQP2), and Na+-K+-2Cl- cotransporter 2 (NKCC2)." (PMID 35444557, 2022). "Accompanied by abnormal expression of AQP2, patients will develop nephrogenic diabetes insipidus, which further confirms the physiological function of AQP2." (PMID 35245343, 2022). "The transport of aquaporin 2 between membrane and storage region is a crucial part of the water reabsorption in renal principal cells, and its malfunction can lead to Diabetes insipidus." (PMID 35534498, 2022). "This suggests that the medullary atrophy is likely to prevent the ability to increase Aqp2 levels sufficiently to concentrate the urine, resulting in a nephrogenic component to the diabetes insipidus." (PMID 26839400, 2016).
diabetes insipidus (continued). "Similar data have been obtained in mice with inducible AQP2 knockdown (“inducible diabetes insipidus”) that exhibit only mildly dilated cortical and medullary collecting ducts, but no microcysts as seen with lithium." (PMID 24744881, 2014). "FXR and TGR5, as bile acid receptors, play an important role in renal water homeostasis through regulating the expression and trafficking of AQP2, which provides a novel therapeutic for the treatment of water and salt metabolism disorders such as diabetes insipidus." (PMID 38033333, 2023). "In cell models,lithium has been shown to downregulate aquaporin-2 transcription and to causenephrogenic diabetes insipidus independent of adenylyl cyclase activity." (PMID 32684112, 2021). "Indeed, we and others previously showed that disruption of actin organization using statins led to the apical membrane accumulation of AQP2 in vivo and to an increase in urine concentration ability in rodent models of diabetes insipidus." (PMID 32340337, 2020). "Previous studies show aldosterone increases urine production and decreases apical AQP2 expression in rats with diabetes insipidus, suggesting that aldosterone may decrease vasopressin-stimulated osmotic water permeability." (PMID 32295252, 2020). "Also, zebrafish models are probably unsuitable to study genetic diseases affecting water homeostasis, such as hereditary nephrogenic diabetes insipidus, which is caused by either AVPR2 or AQP2 defects in humans." (PMID 30200518, 2018). "Defects preventing the insertion of AQP2 into the plasma membrane lead to diabetes insipidus." (PMID 26903868, 2016). "These events may activate the Ca sensing receptor expressed in apical membranes in inner medullary collecting duct and enhance basal autophagy, resulting in autophagic degradation of AQP2 and subsequently contributing to development of nephrogenic diabetic insipidus." (PMID 30941057, 2019). "Thus, inability to increase Aqp2 expression is in keeping with a generalised homeostatic failure of the distal nephron and, in Col4a1 mutant mice, leads to a failure to concentrate urine and diabetes insipidus." (PMID 26839400, 2016). "DI: diabetes insipidus; ADH: antidiuretic hormone; AVP: arginine vasopressin; AQP2: aquaporin-2 receptors." (PMID 33786230, 2021). "The modulation of the protein complex may lead to novel concepts for the treatment of disorders which are caused or are associated with dysregulated AQP2 and for which a satisfactory treatment is not available, e.g., hyponatremia, liver cirrhosis, diabetes insipidus, ADPKD or heart failure." (PMID 32164329, 2020). "A decrease or increase in urinary AQP2 levels was shown to correspond with diminished or exaggerated levels of AVP, as seen in central diabetes insipidus or SIADH, respectively." (PMID 22325688, 2012).
Hyponatremia (31 papers, 2012 to 2025). An abnormally decreased sodium concentration in the blood. "On the other hand, water retention and hyponatremia caused by excessive activation of AQP2 are often difficult to manage and worsen the prognosis of patients with heart failure and hepatic cirrhosis." (PMID 34884753, 2021). "There has recently been evidence supporting the efficacy and safety of the AQP2 antagonist (tolvaptan) in the treatment of hyponatremia caused by renal function in patients with acute or chronic heart failure." (PMID 34903939, 2021). "Dysregulation of AQP2 is also a cause of water retention with hyponatremia in heart failure, hepatic cirrhosis, and syndrome of inappropriate antidiuretic hormone secretion (SIADH)." (PMID 34884753, 2021). "It has been found that dysregulation and dysfunction of AQP2 cause many disorders related to water balance in people and animals, including polyuria and dilutional hyponatremia." (PMID 27409611, 2016). "Early-stage HF is associated with blunted increase in AQP2 and p(Ser256)-AQP2 despite of hyponatremia, hypo-osmolality, and increased inner medullary vasopressin V2 receptor expression." (PMID 25658446, 2015). "Future studies are necessary to clarify how renal prostaglandins are involved in producing TIH and whether other pharmacogenetic variants of AQP2 and its upstream modifiers are associated with drug-induced hyponatremia." (PMID 36233678, 2022). "On the other hand, direct action of the drug on the kidney for AQP2 upregulation or induction of the NSIAD may underlie most cases of drug-induced hyponatremia." (PMID 34955900, 2021). "Results showed that Ec induced an increase in AQP2 expression, evidencing another mechanism that might contribute to cause rapid hyponatremia." (PMID 28678861, 2017). "Vice versa, up-regulation of the system causing a predominant localization of AQP2 in the plasma membrane leads to excessive water retention and hyponatremia as in the syndrome of inappropriate antidiuretic hormone secretion (SIADH), late stage heart failure or liver cirrhosis." (PMID 26903868, 2016). "Stroke patients with hyponatremia present elevated urinary AQP2 and plasma vasopressin levels despite reduced osmolality, suggesting non-osmotic AQP2 regulation and possible kidney-brain fluid imbalance." (PMID 40564125, 2025). "This occurs through increased transcription and insertion of water channels (Aquaporin-2) into the apical membrane of distal convoluted tubule and collecting duct epithelial cells, ultimately leading to hyponatremia." (PMID 29499058, 2018). "The abundance and plasma membrane localization of AQP2 is increased, which leads to excessive water retention and hypervolemic (dilutional) hyponatremia." (PMID 26903868, 2016). "In conclusion, urine aquaporin-2 is a novel predictor of responsiveness to tolvaptan, and the responders achieved amelioration of symptomatic congestion, normalization of hyponatremia, and improvement in renal function during tolvaptan treatment." (PMID 26784173, 2016). "HF rats developed hyponatremia, hypo-osmolality, increased HR, and decreased levels of fractional urinary excretion of sodium, but exhibited comparable IM AQP2 and p-AQP2 abundance with Sham rats 17 days after MI." (PMID 25658446, 2015). "Notably, drugs that can induce hyponatremia in humans have a common mechanism of action: AQP2 upregulation via V2R stimulation." (PMID 39202754, 2024). "AVP manages serum osmolality via V2 receptors and hence AQP-2 water channels of the renal epithelial cells of collecting ducts are stimulated with the V2- vasopressin receptor and therefore leads to water retention and hyponatremia." (PMID 38812639, 2024). "Stimulation of the intracellular machinery, leading to localization of AQP2 at the apical plasma membrane, results in abnormal water retention and consequent hyponatremia as in the syndrome of inappropriate antidiuretic hormone (SIADH) secretion, liver cirrhosis, and congestive heart failure." (PMID 33633156, 2021).
Hyponatremia (continued). "Thus, in the case of increased expression of AQP2, excessive water reabsorption and subsequently hyponatremia occur." (PMID 33228240, 2020). "Indeed, short-term liver cirrhosis studies have revealed that decreased AQP2 expression is possible in the presence of hyponatremia, hypoosmolality, and sustained elevated AVP." (PMID 25658446, 2015). "Thus, increased urinary AQP2 excretion, in the setting of euvolemic hyponatremia and low or undetectable levels of serum AVP, suggests the possibility of NSIAD." (PMID 22325688, 2012). "However, others including antipsychotics, antidepressants, anticonvulsants, cyclophosphamide, and thiazide diuretics may induce hyponatremia by intrarenal mechanisms for aquaporin-2 (AQP2) upregulation, compatible with NSIAD." (PMID 36233678, 2022). "Additionally, CY might cause hyponatremia by upregulating expression of ADH receptor V2R and aquaporin 2 through suppression of interleukin-1 and tumor necrosis factor-α, which act as negative regulators of VR2 expression." (PMID 33235058, 2020). "In conclusion, our data showed that Ec was able to directly stimulate the increase of AQP2 in IMCD cells, evidencing, for the first time, the existence of another mechanism that intensifies water absorption quickly, increasing the hyponatremia." (PMID 28678861, 2017). "In the renal collecting duct both short-term and long-term regulation of AQP2 is activated by sustained elevation of AVP, participating in renal water retention and dilutional hyponatremia." (PMID 26239456, 2015). "The mechanism by which SSRIs, such as fluoxetine and sertraline, can induce hyponatremia has been explored in experimental studies, and it was found that they upregulate aquaporin-2 (AQP2) in the kidney without arginine vasopressin." (PMID 39202754, 2024). "In brief, drug-induced hyponatremia can be largely explained by AQP2 upregulation from V2R-cAMP-PKA signaling in the absence of AVP stimulation." (PMID 34955900, 2021). "In the renal collecting duct, the aquaporin-2 (AQP2) water channel is regulated by sustained elevation of AVP release, and this leads to augmented hydroosmotic action of AVP, that results in exaggerated water retention and dilutional hyponatremia." (PMID 26239456, 2015). "Of note, DM per se (in the absence of hyperglycemia) may lead to hyponatremia, possibly through induction of aquaporin-2 (AQP2) by insulin." (PMID 33228240, 2020). "Thus, in certain settings of extracellular fluid volume expansion, excessive water retention with hyponatremia can occur in the absence of increased AQP2 abundance." (PMID 25658446, 2015).